TLR2 (toll like receptor 2)
Diseases named in the same sentence as TLR2 in open-access papers (continued):
Sharing a sentence is not in itself a finding about the gene and the disease.
infection (continued). "Real-time SG uptake analyses showed that both unprimed and TLR2-primed primary Gsdmd-/- macrophages displayed a delayed membrane permeability increase upon MNV infection." (PMID 31017981, 2019). "In fact, the infection with L. braziliensis increased the expression of TLR2 and TLR4 on intermediate monocytes." (PMID 31119102, 2019). "A similar result has been reported in the HSV genital infection model, as both TLR9 and TLR2 together have been observed to be relevant for resisting intravaginal infection by HSV-1." (PMID 31114761, 2019). "In the early phase of infection, TLR2 signalling has an anti-inflammatory role, perhaps to prevent a detrimental overwhelming inflammation as a result of the activation of other PRRs." (PMID 30452654, 2019). "Our quantitative real-time PCR analysis showed that the number of parasites in the brains of the TLR2-/- mice was significantly higher than that of the TLR2+/+ mice at 30 days after infection (p = 0.0315)." (PMID 31404078, 2019). "Another highly relevant category of genes of which the induction or repression during infection is dependent on Tlr2 includes the chemokines." (PMID 31747871, 2019). "In the current study, to further explore the involvement of Tlr2 in Mm infection, we conducted infection studies using tlr2 mutant zebrafish." (PMID 31747871, 2019). "Our results reveal that infection with L. braziliensis increases the expression of TLR2 and TLR4 on inflammatory monocyte subsets and this increase is accomplished mainly by TNF production." (PMID 31119102, 2019). "We also performed Sub-Network Enrichment Analysis (SNEA) to identify possible key genes that are responsible for the difference in response of the tlr2+/− and tlr2−/− group to Mm infection (P < 0.05)." (PMID 31747871, 2019). "The tlr2 mutant is therefore a valuable model for further studies using published infection models for other pathogens and the study of the interactions with gut microbiota in zebrafish larvae." (PMID 31747871, 2019). "At 45 min post-infection with S. aureus, there was already a significant reduction in the number of intracellular bacteria within TLR2 knockout THP-1 cells compared with WT cells." (PMID 31558608, 2019). "The effect of TLR2 on mouse survival during an infection with T. gondii is both dose and parasite strain dependent." (PMID 31404078, 2019). "In fact, infection with T. gondii decreased the time spend in freezing activity in both TLR2+/+ and TLR2-/- mice in the context test." (PMID 31404078, 2019). "During primary infection, TLR2 is likely activated by EBV surface glycoprotein gp350, which also binds to cellular receptor CD21 to mediate viral entry and membrane fusion." (PMID 31238570, 2019). "Our study shows that Tlr2, as a part of innate immunity, plays an important role in controlling mycobacterial infection as observed on the transcriptome and infection level." (PMID 31747871, 2019). "Based on our results, we put forward that TLR-2-mediated alteration in (Ca2+)c level acts as innate immune mechanism that triggers downstream signals to help host overcome perceived threat of infection." (PMID 31444398, 2019). "For instance, C57Bl/6 MyD88-null mice are more susceptible to infection with L. major than wild type animals while C57BL/6J TLR2−/− mice infected with L. braziliensis are more resistant to infection than C57BL/6J wild type mice." (PMID 31119102, 2019). "In other infection systems, Tlr2 mutant mice have an increased resistance against infection of Candida albicans and Yersinia pestis." (PMID 31747871, 2019). "TLR2 and TLR5 expression differences have been noted in macrophage-like cells as well: infection with Borrelia burgdorferi upregulated both TLR2 and TLR5 expression in microglial cells, but only TLR2 was upregulated in monocytes." (PMID 31774834, 2019).
infection (continued). "RNAseq analysis of infected tlr2−/− versus tlr2+/− shows that the number of up-regulated and down-regulated genes in response to infection was greatly diminished in tlr2 mutants by at least 2 fold and 10 fold, respectively." (PMID 31747871, 2019). "The transcriptome and infection burden analyses show a function of Tlr2 as a protective factor against mycobacteria." (PMID 31747871, 2019). "With respect to the number of genes affected, the strongest effect was observed in genes that are down regulated during infection, since this category was strongly diminished in the tlr2 mutant." (PMID 31747871, 2019). "The vitamin D receptor pathway genes that are normally up-regulated during infection in zebrafish larvae were down regulated in the tlr2 mutant." (PMID 31747871, 2019). "Since schistosomal lipids were described as a TLR2 signaling pathway activators in murine infections, we checked if human eosinophils were able to express TLR2." (PMID 30740113, 2018). "Due to its ability to form heterodimers with either TLR1 or TLR6, TLR2 can sense a broad spectrum of microbial as well as endogenous ligands indicating its importance both in infection and autoimmunity." (PMID 29593720, 2018). "During infection, TLR2 and TLR4 signaling are important for the initial host defense against bacterial lipopolysaccharide (LPS) and heat shock proteins, whereas TLR3 and TLR9 are mainly responsible for recognizing microbial nucleic acids in mice." (PMID 30564215, 2018). "Another notable observation of the present study was elevated expression level of TLR2 in host MΦs following Bm-L3 infection." (PMID 29483912, 2018). "HSPCs express Toll-like receptors (TLR), such as TLR4 and TLR2, enabling them to recognize and respond to infection." (PMID 29898768, 2018). "More importantly, the area of granuloma formation and fibrosis surrounding single eggs in the livers of TLR2-/- mice were significantly lower compared with that of WT mice at 6 weeks post-infection." (PMID 30589840, 2018). "Our data suggest that the combination of the use of cyclophosphamide with the compound measurement of B cells, Th17 cells, and TLR2 expression in monocytes is useful as an infection predictive index in SLE patients." (PMID 30692998, 2018). "The results showed that TLR2 was significantly up-regulated in blood cells at 2, 3, and 4 h post-infection with SS2 ZY05719." (PMID 30581435, 2018). "That induction is mediated by linking L. (V. ) braziliensis-LPG to TLR2, indicating the crucial role of that receptor in innate defenses against infection." (PMID 29543867, 2018). "Unexpectedly, the miRNA profile of infected TLR2−/− macrophages revealed low levels of miRNA modulation during the course of infection." (PMID 30555476, 2018). "The comparison between WT and TLR2−/− macrophages showed increased levels of the Arg1 transcript 4 h after infection and decreased levels of Nos2 transcript in all infection periods analyzed (respectively)." (PMID 30555476, 2018). "The importance of TLR2 and TLR9 in the recognition of infection with herpes simplex virus (HSV) and HSV-caused diseases has been described, but some discrepancies remain concerning the benefits of these responses." (PMID 29760708, 2018). "Recent work in CD4 +T cells has similarly demonstrated enhanced infection and/or viral production in T cells on stimulation of TLR2." (PMID 30520725, 2018). "P. acnes/PGN induced the expression of TLR-2 in a multiplicity of infection (MOI)-/dose- and time-dependent manner in HaCaT and SZ95 cells at the mRNA levels, compared with control." (PMID 29507345, 2018). "Recent studies have focused on TLR2 and TLR4, as these TLRs recognize the widest range of microbial components involved in PD-associated infections and are also the main TLRs involved in sterile inflammatory responses." (PMID 30538643, 2018). "In this experimental setting, we observed that TNF-α production was impeded because of TLR2-deficiency upon BCG and M. tuberculosis infection." (PMID 29712918, 2018).
infection (continued). "Previous studies showed that live N. caninum tachyzoites can induce TLR2 upregulation and regulate the production of inflammatory cytokines to control the infection of N. caninum." (PMID 30087675, 2018). "During infection, TLR2 signaling promotes both activation of DCs and development of the Th1 and Th17 immune response, which together induces neutrophil recruitment to the spleen and liver." (PMID 28280488, 2017). "In fact, some studies showed that TLR2-defective mice infected with C. albicans are less resistant to infection, due to their inability to release TNF-α and MIP-2 or TNF-α, IL-12 and IFN-γ." (PMID 28344593, 2017). "In general, anti-DenV2 sera derived from DenV2-infected BL/6, TLR2 KO, and MyD88 KO mice were unable to completely neutralize DenV2 or DenV4 infection." (PMID 29285314, 2017). "CSFV Shimen infection results in a significant induction of TLR2, TLR4, and TLR7, but decreased of TLR3." (PMID 28751780, 2017). "After infection, the expression of TLR2 was induced but comparatively more expression was observed in Ms_rv0774c." (PMID 28713776, 2017). "TLR9−/− neutrophils presented a normal activation profile during infection, while TLR2−/− neutrophils presented a defective effect on the expression of CD11b, an integrin expressed on the surface of neutrophils." (PMID 28280488, 2017). "A protective role during infection was proposed for TLR2 as one of the molecules involved in Leishmania phagocytosis." (PMID 28288677, 2017). "In opposition, other groups have reported that TLR2-defective mice are more resistant to infection due to increased chemotaxis and candidacidal capacity of macrophages." (PMID 28344593, 2017). "Compared with PBS controls, sublethal infection also markedly induced mRNA levels of TLR2, IFN-γ, TNF-α, CXCL9, CXCR3, and Ang2." (PMID 28742087, 2017). "In the present study, TLR2 Ab and PAR siRNA had additive inhibitory effects, suggesting that infection of microglia with P. gingivalis activates gingipain/PAR2 system to induce neuroinflammation in a manner parallel to P. gingivalis LPS/TLR2 system." (PMID 28924232, 2017). "This suggests a positive proviral role of these TLR2-positive cells for the establishment of a persistent infection in immune-competent mice." (PMID 28452930, 2017). "In vivo, TLR2 signaling promotes the survival of P. gingivalis and enables infection to drive dysbiosis and alveolar bone resorption." (PMID 28848717, 2017). "In gram‐positive bacteria the release of Lpp into the supernatant is crucial for the immune modulation via TLR2 activation thus contributing to inflammation and infection." (PMID 28901671, 2017). "The mRNA expression level of type I IFNs during HSV-1 infection was evaluated in the TG of WT and TLR2/9−/− mice on the 5th day after infection using qPCR." (PMID 28222752, 2017). "This endocytic process upon TLR2 ligation closely resembles the infection process of various viruses in host cells." (PMID 29285314, 2017). "IFN-β transcript, however, is detected in both WT and TLR2/9−/− mice in the TG on the 5th day after infection, indicating that this response seems to be TLR-independent." (PMID 28222752, 2017). "The positive ADE regulation of DenV2 and DenV4 infectivity by TLR2/MyD88 pathway in primary anti-DenV2 sera was more evident when relative fold of infection enhancement to control was comparably displayed with the amount of total IgG protein." (PMID 29285314, 2017). "Mechanistically, DCs are activated during infection in a TLR2-dependent manner, promoting prototypal Th1 and Th17 subsets and CXCL1 production." (PMID 28280488, 2017). "High levels of iNOS/NO responses are favorable to C. sinensis development in the TLR2 mutant mice at the early stage of infection." (PMID 28784165, 2017). "In this experiment, we investigated iNOS/NO expression and development of C. sinensis, which are possibly influenced by TLR2 signaling during the infection, in natural ‘low responders’ C57BL/6 J mice." (PMID 28784165, 2017).
infection (continued). "TLR2 has been previously demonstrated to be important in survival of LVS infection in B6 genetic background mice." (PMID 28360906, 2017). "Since staphylococci and their lipopeptides are being recognized by TLR2, we investigated the expression of TLR2 on mRNA level in the two murine infection models." (PMID 28428684, 2017). "TLR2 is induced during infection and is important for DC activation, which influences the drive of naïve CD4+ T cells to the Th1 and Th17 pattern as well as the production of CXCL1." (PMID 28280488, 2017). "TLR2−/− mice harbored more parasites in both target organs during weeks 4 and 6 after infection than WT animals." (PMID 28280488, 2017). "CW components are highly inflammatory in many models of infection, a property conveyed by recognition by the innate immune receptor Toll-like receptor 2 (TLR2) on the plasma membranes of phagocytes and epithelial and endothelial cells (4, –, 7)." (PMID 28049146, 2017). "Over-expression of TLR2 in transgenic dairy goats is a useful model for studying various aspects of infection with Gram-positive bacteria, in vivo." (PMID 28078083, 2017). "TLR2-dependent osteoclast differentiation and bone resorption in response to infection with S. aureus and B. abortus were also shown to be MyD88 dependent." (PMID 28848717, 2017). "Bacterial clearance from the lungs was slightly impaired in TLR2−/− mice after low‐dose infection only; bacterial elimination from the lungs was slightly accelerated in the TLR2−/− mice after high‐dose infection." (PMID 29142002, 2017). "The WT mice showed an increase in IFN-β mRNA level, which reached a higher level of expression at 24 h post infection, while the TLR2/9−/− mice exhibited a marked decrease in the mRNA level of this cytokine at this time." (PMID 28222752, 2017). "Virulent IOE infection triggers upregulation of several TLRs in liver tissue of infected mice including TLR2, TLR7, and TLR9." (PMID 29049365, 2017). "Infection of S. aureus causes the recruitment of active Rho GTPases Rac1 and PI3K to the TLR2 cytosolic domain." (PMID 28165033, 2017). "The contribution of TLR2 to host defense against S. aureus appears to depend on the site of infection." (PMID 29142002, 2017). "Although C57BL/6 TLR2−/− mice develop a higher bacterial burden compared to C57BL/6 wild-type mice in the infection with O. tsutsugamushi, C57BL/6 TLR2−/− mice show milder symptoms of disease and enhanced survival rates." (PMID 28770333, 2017). "EBV has been reported to induce an innate immune response characterized by strong release of IL-8 and MCP-1 via TLR9 and TLR2 in monocytes shortly after infection." (PMID 28245863, 2017). "The genetic associations between TLR2, TLR4 and NOD2 polymorphisms with susceptibility to infections, on the one hand, and BD, on the other, have been previously reported in the literature." (PMID 28075410, 2017). "By contrast, following intranasal infection, the Slc11a1+ and Slc11a1+Tlr2/4/9−/− mice accumulate very little cytokine in either in serum or lung after intranasal infection." (PMID 28360906, 2017). "This work demonstrates that TLR2 displays a protective role in the control of parasite replication in target organs of infection." (PMID 28280488, 2017). "In this regard, our data presented in this study provide the first insight into the important role of Th2-biased immune responses induced by primary DenV infection and their TLR2 dependence in favoring secondary infection to DHF/DSS." (PMID 29285314, 2017). "Because we observed DCs to be productively infected by DenV2, we decided to explore the impact of TLR2 on the DenV2 infection process in DCs." (PMID 29285314, 2017). "The expression of TLR2 and subsequently NF-kB was decreased in intestinal schistosomiasis 12 weeks after infection even though the parasite burden is still high." (PMID 29225962, 2017). "Primary anti-DenV2 sera obtained from TLR2 KO and MyD88 KO mice showed lower fold of infection enhancement than those from BL/6 mice." (PMID 29285314, 2017).
infection (continued). "Strikingly, the fates of ΔMMAR_2321 and ΔMMAR_2331 in the early infection events seem to be TLR2- and CR3-independent." (PMID 29183333, 2017). "C57BL/6 TLR2−/− mice, however, are more resistant to lethal infection with O. tsutsugamushi compared to C57BL/6 wild-type mice." (PMID 28770333, 2017). "LPG purified from L. major has been proven to be the main TLR2 agonist, since this receptor participates in the recognition of Leishmania and activation of an important pathway in infection control." (PMID 29358935, 2017). "Phagocytosis of S. aureus by alveolar macrophages in vivo after low‐dose infection was unimpaired, but viability of ingested bacteria was significantly greater in TLR2−/− mice." (PMID 29142002, 2017). "The microarray data indicated that TLR expression in chicken B cells exhibited a distinct pattern in response to vvIBDV infection, with decreases in the expression of TLR2, TLR6, and TLR7." (PMID 28086922, 2017). "Bronchiolar and alveolar inflammation was readily apparent 24 h after intermediate dose infection in WT mice, but these lesions were less severe in TLR2−/− animals, in agreement with the BAL findings." (PMID 29142002, 2017). "It is difficult to assess the role of TLR2/4 in immune protection or pathogenesis of infection in an in vitro model because inflammation is a very complicated process that involves several types of immune cells and cytokines." (PMID 29016688, 2017). "Research with different experimental models suggests that the role of TLR2 in resistance to S. aureus depends on the route of infection." (PMID 29142002, 2017). "The kinetics of IL-1β mRNA transcription in peritoneal Mφ from WT and TLR2/9−/− mice were analyzed by qPCR at different time points following in vitro infection." (PMID 28222752, 2017). "Upon infection with Leptospira sp., iNOS is expressed 3 days post-infection in kidneys and lungs of mice in a TLR2- and TLR4-dependent manner." (PMID 28270811, 2017). "Research showed that TLR2-/- mice presented higher parasite burden than wild-type mice at acute and chronic stages of infection by N. caninum with diminished IFN-γ/IL-10 ratio." (PMID 28798732, 2017). "The area under the curve (AUC) analysis of lesion development also demonstrates elevated AUC values in L. mexicana infected TLR2−/− mice when compared to WT mice after infection with either promastigote or amastigote parasites." (PMID 27716391, 2016). "Above study indicated that TLRs were differentially distributed among various CNS cell types upon infection, e.g., TLR2 was localized to nervous tissue cells, particularly astrocytes, but TLR4 was localized to microglia and neurons." (PMID 27511368, 2016). "By the second week of infection, the TLR2−/− mice displayed significantly greater ankle swelling than the WT control mice, and this exacerbated response continued past day 35 postinfection." (PMID 27857714, 2016). "This suggests that TLR2 is important in controlling lesion development upon infection with both species." (PMID 27716391, 2016). "We determined that E. chaffeensis activates the canonical Notch signaling pathway, and this pathway suppresses TLR2/4 expression during infection." (PMID 27381289, 2016). "Further, BODIPY analysis of the lungs by IF and FACS and ORO staining validated the TLR2-dependent FM generation in mice during H37Rv infection." (PMID 27532872, 2016). "In the brain isolated from mice at 2 days post-infection (dpi) with Acanthamoeba strains Ac55 and Ac43, mRNAs for TLR2 and TLR4 were significantly more strongly expressed in comparison with the uninfected mice." (PMID 27511368, 2016). "Blocking of TLR2 activation or heat denaturation of OMVs restored bacterial replication in the first 24 h of infection." (PMID 27105429, 2016). "Previous studies have demonstrated that production of a mature IL-1β after MVA infection requires a crosstalk between TLR2-MyD88 and NALP3 inflammasome." (PMID 27223301, 2016).